HMOX1 (heme oxygenase 1)
Diseases named in the same sentence as HMOX1 in open-access papers (continued):
Sharing a sentence is not in itself a finding about the gene and the disease.
tumor (continued). "Further, spatially resolved transcriptomics confirmed the spatial overlap between exhausted T cells and HMOX1+ myeloid cells, spatially localized within regions of the tumor enriched for mesenchymal transcriptional signatures." (PMID 35177622, 2022). "HMOX1 has been found to be involved in the multiple steps of tumor metastasis including invasion, intravasation, extravasation, and colonization." (PMID 36033490, 2022). "As a survival-enhancing molecule of AML, Heme oxygenase-1 (HO-1) promotes tumor progression, carcinogenesis, and chemical resistance." (PMID 36452482, 2022). "Emerging evidence has indicated the effect of HMOX1 in tumor metastasis, and HMOX1 is attractive as a potential prognostic biomarker and therapeutic target." (PMID 36033490, 2022). "And two FRGs, STEAP3 and HMOX1, formed a synergistic effect on the occurrence of ferroptosis in tumor cells." (PMID 35501667, 2022). "Pharmacological inhibition of HMOX1 is considered a promising therapeutic approach to hinder tumor metastasis." (PMID 36033490, 2022). "Among those proteins, heme oxygenase 1 (HO‐1) exerts antioxidant and apoptotic effects, facilitating carcinoma cell proliferation and resistance to anti‐tumor therapy." (PMID 34264023, 2022). "Herein, we specifically focused on HMOX1, the gene coding for HO‐1, which was significantly overexpressed in BMDMs compared to resident MG and tumor cells." (PMID 36054818, 2022). "Previous studies have shown that HMOX1 is elevated in various malignant tumors, can prevent drugs from attenuating the increase in ROS, and can also promote tumor cell proliferation and metastasis." (PMID 34975326, 2022). "Among them, high HMOX1 expression was in relation to increased infiltration levels of tumor-infiltrating immune cells across GC." (PMID 35903347, 2022). "Currently, pharmacological inhibition of HMOX1 is considered a promising therapeutic approach to hinder tumor metastasis." (PMID 36033490, 2022). "The un-translation at the exon 3 of the HMOX1 gene generates a 14 kDa HO-1 protein, which plays a role in modulating telomere length and tumor growth." (PMID 34572050, 2021). "Proteins related to cell proliferation, growth, and apoptosis like BCL-X, HIF-1α, HNF-3β, and HO-1/HMOX1 were also downregulated, that is, related to tumor progression, whereas upregulation of E-cadherin (CDH1) was observed after chrysin treatment." (PMID 35096000, 2021). "At the posttranscriptional level, it has recently been reported the expression of a 14 kDa HO-1 protein, generated by exon 3 skipping of HMOX1 gene, in human normal and tumor cell lines." (PMID 33440611, 2021). "We present evidence that nab-paclitaxel–gemcitabine (NPG) and/or a hypoxic tumor microenvironment (TME) up-regulate heme oxygenase-1 (HO-1), providing a survival advantage for tumors." (PMID 34066839, 2021). "Upregulated HO-1, encoded by the HMOX1, further maintained ROS within a tumor-promoting level and induced cytoprotective autophagy formation." (PMID 34039348, 2021). "By contrast, the increase in Hmox1 levels in the tumor tissues was higher in Nrf2-KO than in WT mice, indicating that transcription factors other than Nrf2 were responsible for it." (PMID 34526660, 2021). "Heme Oxygenase-1 overexpression reduced tumor burden, induced cell cycle arrest and apoptosis, and decreased cell migration and invasion, impairing metastatic dissemination, which reflects an antitumor role." (PMID 33440611, 2021). "The results evidenced a significant positive correlation between MX1 and HMOX1 expression profiles, both in human tumor and normal adjacent to tumor tissue samples." (PMID 32640729, 2020). "This subpopulation differentially expresses genes that have been shown to be tissue-reparative (Hmox1, Gas6) and tumor-promoting (Pf4, Fgfr1, and Nrp2)." (PMID 33072601, 2020).
tumor (continued). "Using the TCGA-PRAD database, we observed a positive correlation in the expression profiles of MX1 and HMOX1, both in normal adjacent to tumor (Pearson = 0.3718; p = 0.0066) and in tumor tissue samples (Pearson = 0.4681; p < 0.0001)." (PMID 32640729, 2020). "Unreasonably, HMOX1 was upregulated in tumor samples, but its expression predicted an excellent prognosis in the univariate Cox analysis, so it was excluded from further study." (PMID 32760210, 2020). "Summarizing, the expression of HMOX1 and the activity of its byproducts can provide the selective advantage for tumor cells to overcome the increased oxidative stress occurring during tumorigenesis and/or as a consequence of anti-tumor therapies." (PMID 32010627, 2019). "These iron-positive macrophages (iTAMs) are hallmarked by low expression of the iron exporter ferroportin and positivity for CD86, CD163, and HMOX1 as well as a pro-inflammatory phenotype with the ability to kill tumor cells." (PMID 31383898, 2019). "For instance, human RCC downregulate CXCR3-B, which results in the upregulation of the anti-apoptotic heme oxygenase-1 (HO-1) and an increased tumor cell proliferation and dissemination." (PMID 31216755, 2019). "Here we investigated the kinetics of early heme oxygenase 1 (HO-1) induction on inflammation, tumour development, and DNA damage in Mdr2−/− mice." (PMID 30389969, 2018). "Usually, pharmacological or genetic induction of HMOX1 facilitates tumor progression while silencing HMOX1 leads to decreased growth in culture cells and in vivo and has been suggested as an antitumor therapy." (PMID 29560114, 2018). "One key mechanism that tumor cells utilize to resist oxidative stress is the overexpression of heme oxygenase 1 (HO-1)." (PMID 29311669, 2018). "Recently, it has been suggested that ATF4 can act in concert with Nrf2 to induce HMOX1 expression as a protective mechanism preventing apoptosis of tumor cells." (PMID 28129777, 2017). "Zinc protoporphyrin (ZnPP), a heme oxygenase-1 (HO-1) inhibitor, is potential to inhibit tumor proliferation and progression." (PMID 26822586, 2016). "The expression of Cd163 and Hmox1 were also significantly increased in monocytes stimulated with G-EVs compared to controls, suggesting that both types of tumor-EVs induced an M2-phenotype." (PMID 27550147, 2016). "This study determined the mRNA levels of Nrf2, Keap1, Bach1, and Hmox1, both in the tumor and in normal tissues, to investigate their correlations in CRC." (PMID 27999449, 2016). "The tumor had lower Hmox1 but higher Bach1 mRNA levels and ratio with Nrf2 than the normal tissue in CRC." (PMID 27999449, 2016). "The lack of significant correlations between Nrf2 and Hmox1 mRNA levels in both the tumor and normal tissues suggests that the transcriptional regulation of Hmox1 by Nrf2 is loose in CRC subjects with distant metastasis." (PMID 27999449, 2016). "The Hmox1/Nrf2 mRNA ratio in the tumor was lower in the subjects with distant metastasis than in those without." (PMID 27999449, 2016). "We therefore further examined different macrophage markers (M1; Nitric oxide synthase 2 (NOS2) and M2; CD163 and Heme oxygenase 1 (HMOX1)) in prostates injected with the different tumor EVs." (PMID 27550147, 2016). "The significant correlations between the mRNA levels of Hmox1 and Nrf2 were lost in both the tumor and normal tissues of CRC subjects with distant metastasis." (PMID 27999449, 2016). "Although the Nrf2/Hmox1 axis is important in tumor progression, Nrf2 and Hmox1 have uncertain roles in cancer metastasis." (PMID 27999449, 2016). "This pattern of enrichment in AC and SCC was also seen with the other NRF2 target genes, GCLC, GCLM and NQO1, although HMOX1 was downregulated in both tumour types." (PMID 27824809, 2016). "The Hmox1/Nrf2 mRNA ratio in the tumor tissue was lower in CRC subjects with distant metastasis than in those without and was a significant predictor of distant metastasis in CRC." (PMID 27999449, 2016).
tumor (continued). "In the tumor tissue with undetectable Bach1 mRNA expression, the correlation between the mRNA levels of Keap1 and Hmox1 was the only one that remained significant." (PMID 27999449, 2016). "The logistic regression with stepwise selection by BIC found that the ratio of Hmox1/Nrf2 mRNA by percentage in the tumor tissue (odds ratio: 0.83; 95% confidence interval: 0.68–0.97) and CEA (1.0027; 1.006–1.064) were predictors for distant metastasis in CRC." (PMID 27999449, 2016). "Hmox1 can protect tissue against oxidative stress and is a key effector of Nrf2 upregulation in tumor progression." (PMID 27999449, 2016). "In these types of cancer, miR-378 seemed to be an oncogene, and enhanced tumor cell survival, promoted tumor growth and metastasis in some tumors via regulation of the target genes SuFu, Fus-1, HMOX1, ESRRG and GABPA." (PMID 24555885, 2014). "Our results suggest that MAT2A is downregulated in cancer tissues of RCC patients and has function of tumor suppressor though repressing the expression of heme oxygenase-1 (HO-1)." (PMID 24636201, 2014). "Further investigations into adipocyte-driven FABP4, HMOX-1 and IL-1β expression in tumor cells revealed that transcriptional upregulation of these factors in vitro correlates with increased protein levels." (PMID 24240026, 2013). "We reveal that exposure to lipids supplied by marrow adipocytes induces expression of lipid chaperone FABP4, pro-inflammatory interleukin IL-1β, and oxidative stress protein HMOX-1 in metastatic tumor cells and stimulates their growth and invasiveness." (PMID 24240026, 2013). "The authors suggest that CDDO prevented tumor formation through upregulation of the antioxidant heme-oxygenase-1 (HO-1) and through inhibition of STAT phosphorylation leading to increased apoptosis, as demonstrated in vitro." (PMID 22778711, 2012). "HMOX1 supports rapid tumor growth, cancer aggressiveness, angiogenesis, and metastasis." (PMID 40739397, 2025). "Moreover, this combination therapy decreased the expression of Rubicon, p62, and heme oxygenase-1, reducing tumor vascular density." (PMID 41019287, 2025). "Besides, the overexpression and over-activation of HMOX1 has been involved in triggering autophagy in tumor development." (PMID 39706989, 2025). "Tumor tissues were weighed and subjected to HE staining, Ki-67, and HMOX1 immunohistochemistry." (PMID 39850572, 2024). "Immunohistochemistry analysis confirmed that the tumor suppressive effect of S.C may indeed rely on activating ROS/USP47/BACH1/HMOX1 axis." (PMID 38195593, 2024). "Depletion of SPP results in inhibition of tumour proliferation and migration both in vitro and in vivo, at least partially through impaired cleavage of the TA membrane protein heme oxygenase 1 (HO-1) and the type II membrane protein FKBP8." (PMID 39513424, 2024). "HMOX1 helps in tumour cell proliferation and resistance to cell death." (PMID 39457550, 2024). "By examining gene expression profile in normal, tumor, and hormone-resistance PC tissues, we can identify key molecular players, such as HMOX-1, that may contribute to PC development and therapy resistance." (PMID 39091910, 2024). "Interestingly, upon Hmox1 upregulation induced by hemin, we observed a significant reduction in the inhibitory effects of cucurbitacin I on macrophage-mediated tumor cell migration and invasion." (PMID 37958903, 2023). "Moreover, both TERT deficiency and dysfunctional telomeres decreased lung tumor implantation and expression of the tumor progression markers Mmp9, Egfr, Hmox1 and c-MET." (PMID 37085672, 2023). "ROS may also promote tumour cell metastasis by increasing vascular permeability and triggering vasodilation through activation of the enzyme heme oxygenase 1 (HO-1), given that HO-1 is able to induce the formation of nitric oxide." (PMID 36701089, 2023). "The heme Oxygenase 1 (HMOX1) pathway is involved in tumor development and treatment resistance, which may affect the efficacy of TKI + IO." (PMID 37031459, 2023).
tumor (continued). "Heme oxygenase 1 (HO-1), a well-known enzyme involved in eliminating oxidative stress, predominantly exhibits anti-inflammatory and immune-suppressive properties when expressed by tumour microenvironment cells." (PMID 38201617, 2023). "In consequence, HMOX1 inhibition was explored to reduce tumor growth." (PMID 36899871, 2023). "In contrast to the epithelial cells, carboplatin treatment led to increased expression of pro-survival factors (Bcl2, Mcl1, Ier3, Ier5, Hmox1) in stromal cell populations, thus preserving their viability and potentially providing a means of stabilizing and prolonging the anti-tumor response." (PMID 37660083, 2023). "Nevertheless, based on the current data, a massive activation of HMOX1 is important to kill HT1080 cells, strongly suggesting the efficacy of an opposite strategy: making tumor cells sensitive to the induction of ferroptosis via the therapeutic overactivation of HMOX1." (PMID 36899871, 2023). "In conclusion, the present study suggested that miR-873-5p may act as a tumor suppressor in GBM progression by downregulating the HMOX1/HIF1α/SPOP signaling axis." (PMID 37382594, 2023). "In addition, HMOX1 was reported to promote lung tumorigenesis in mice, and its high expression was correlated with tumor invasiveness in NSCLC." (PMID 37085672, 2023). "mRNA expression of Mmp9, Egfr and Hmox1 (tumor progression), Timp1 and Timp2 (inhibitors of metalloproteinases) and Hif1α (hypoxia) evaluated in lung homogenates was significantly augmented in LLC-challenged Igf1rfl/fl mice, remaining unaltered in CreERT2 mice." (PMID 35688943, 2022). "In addition, myeloid HMOX1 promoted the extravasation and colonization of tumor cells at the metastatic loci." (PMID 36033490, 2022). "HMOX1 activity could also facilitate transendothelial migration of tumor cells, which implicates a potential role for HMOX1 in intravasation and extravasation events." (PMID 36033490, 2022). "TAMs, through expressing heme oxygenase-1 (HO-1), an enzyme that inhibits immune system, suppress the endothelial cells’ response to tumor necrosis factor-a (TNFα), an immunogenic cytokine, and then maintain the immunosuppressive tumor microenvironment." (PMID 36479071, 2022). "Additionally, the HMOX-1 inducer Hemin notably enhanced CTX-mediated tumor inhibition in vitro and in vivo through a mechanism that involved interfering with the ferroptosis process." (PMID 35264971, 2022). "Here we suggest that HMOX1 may also function as a tumor suppressor by increasing apoptosis, which merits more detailed future investigation." (PMID 36457077, 2022). "Heme oxygenase-1 (HO-1)-mediated ferroptosis is an anti-tumor therapeutic strategy, and betulinic acid has different effects on HO-1 at different concentrations, thereby decreasing the expression of HO-1 at low concentrations and increasing it at high concentrations of HO-1 expression." (PMID 36686700, 2022). "In addition, a recent study has identified a novel macrophage subtype, endowed with high heme catabolism by HMOX1, as a pro-metastatic tumor microenvironment remodeling factor favoring EMT." (PMID 36033490, 2022). "Finally, we observe the changes in tumor volume, the expression of inflammation-related genes, and tumor immune cell infiltration in the tumor to explore the synergistic mechanism of HMOX1/MMP9/TNFRSF11B and PD1/PD-L1 in HCC." (PMID 36189226, 2022). "Therefore, the ferroptosis pathway tended to be altered by CTX in tumor cells, which at least partially involved HMOX-1 regulation." (PMID 35264971, 2022). "Moreover, HMOX1/HO-1 (heme oxygenase 1) was reported to promote lung metastasis in mice, and its high expression was correlated with tumor invasiveness in NSCLC, as similarly reported for HIF-1α." (PMID 35688943, 2022). "However, HMOX1 has also been demonstrated to promote tumor progression and metastasis in multiple cancers such as glioma, colorectal cancer, melanoma, breast cancer, and others." (PMID 36033490, 2022).
tumor (continued). "SIRT-4 can regulate the phosphorylation of P38 mitogen-activated protein kinase (MAPK) to control reactive oxygen species (ROS) level and heme oxygenase-1 expression, change the tumor hypoxia microenvironment, promote the apoptosis of cancer cells, and play an anti-tumor effect." (PMID 35906622, 2022). "HMOX1 expression levels were significantly elevated in tumor samples compared to normal controls." (PMID 34858984, 2021). "Interestingly, however, the mRNA and the protein levels for heme oxygenase 1 (Hmox1), which is also partly regulated by Nrf2, were profoundly increased in tumor vs. peri-tumoral tissues." (PMID 34526660, 2021). "Furthermore, in 43 paired tumor samples and normal adjacent tissue samples analyzed from the TCGA database, HMOX1 expression was lower in tumor samples than in normal adjacent tissue samples." (PMID 34503136, 2021). "Moreover, high expression of heme oxygenase-1 (HO-1) in tumors can inhibit tumor cell apoptosis and immunostimulatory effects." (PMID 33628585, 2021). "Additionally, the HIF-1-regulated vascular tone-modulating endothelin 1 (EDN1) and heme oxygenase 1 (HMOX1) transcripts were significantly suppressed throughout the entirety of LUAD tumor development." (PMID 34940617, 2021). "Finally, he described a subset of TAM (F4/80high) which overexpress HO-1 (heme-oxygenase-1) that plays a critical role in promoting tumor metastasis and immunosuppression." (PMID 34539674, 2021). "We previously showed that heme oxygenase 1 (HO-1), a cellular homeostatic regulator counteracting oxidative and inflammatory damage, exhibits anti-tumoral activity in PCa cells, inhibiting cell proliferation, migration, tumor growth and angiogenesis." (PMID 34208670, 2021). "In addition, HMOX-1 expression was higher in normal tissues than in tumor tissues in the GEO database (GSE3524)." (PMID 34503136, 2021). "Furthermore, HMOX1 has been widely recognized to play a cytoprotective role in tumor cells to overcome the assault of enhanced oxidative stress in the tumor microenvironment, thereby preventing the cancer cells from apoptosis and autophagy." (PMID 34858984, 2021). "Current studies suggested that high levels of antioxidant genes such as gamma-glutamyl-transpeptidase, glutathione-S-transferase, glutathione peroxidase 3, 4 and heme oxygenase 1 (HO-1) 5 may be involved in tumor chemotherapeutic resistant mechanism." (PMID 32047536, 2020). "However, the efficacy of HMOX1 modulation specifically toward tumor angiogenesis has yet to be investigated." (PMID 32082188, 2020). "In addition to its primary role in heme catabolism, HMOX-1 also modulates tumor microenvironment and impacts cancer progression through its anti-oxidative and anti-inflammatory functions." (PMID 32537435, 2020). "Of note, AEM1 was also able to decrease the NRF2-dependent induction of HMOX1 in H838 and H460 NSCLC cells with LOF mutations of the KEAP1 gene, suggesting that AEM1 might preferentially target tumor cells with constitutive NRF2 activation." (PMID 32106613, 2020). "In particular, the inactivation of the heme-degrading enzyme heme oxygenase-1 (HMOX1) is lethal in the context of hereditary leiomyomatosis and renal-cell cancer (HLRCC), a form of tumor characterized by germline mutations in the gene encoding for the enzyme fumarate hydratase." (PMID 30941311, 2019). "The protective effects of HMOX1 are essential for tumor cell proliferation." (PMID 29560114, 2018). "Moreover, genetic and pharmacological inhibition of iron-related genes (e.g., HO-1, TfR1, and FTH1, which encode heme oxygenase-1, transferrin receptor 1, and ferritin, respectively) can inhibit ferroptosis in tumor cells." (PMID 28657578, 2017). "The tumor had lower Hmox1 and higher Bach1 mRNA levels than the normal tissue." (PMID 27999449, 2016). "Nrf2 and Hmox1 can protect cells from oxidative stress and play roles in tumor metastasis." (PMID 27999449, 2016). "The tumor had lower Hmox1 but higher Bach1 mRNA levels than the normal tissue." (PMID 27999449, 2016).